S100A2 (S100 calcium binding protein A2)
Diseases named in the same sentence as S100A2 in open-access papers (continued):
Sharing a sentence is not in itself a finding about the gene and the disease.
tumor (continued). "These different studies highlight a potential tumor-specific regulatory mechanism for S100A2 in glucose metabolism." (PMID 40011447, 2025). "As evidenced by clinical data, the analysis indicates that S100A2 is upregulated in the later stages of tumor metastasis." (PMID 40011447, 2025). "HE staining also revealed more pronounced tumor infiltration in the lung tissue of the S100A2-OE group." (PMID 40011447, 2025). "As confirmed by HE staining, which also revealed more pronounced tumor infiltration in the lung tissue of the S100A2-overexpressed group." (PMID 40011447, 2025). "We also identified a distinctive subset of S100A2+ PDAC tumor cells associated with LNM and validated the functional significance of S100A2 through wound healing and transwell migration assays." (PMID 40092486, 2025). "Additionally, variations in the tumor microenvironment, such as oxygen availability, nutrient supply, or specific oncogenic mutations, could influence the choice of glucose transporters and pathways engaged by S100A2." (PMID 40011447, 2025). "Collectively, these findings underscore the pivotal role of an S100A2+ tumor cell subset in orchestrating LNM in PDAC, indicating its potential value in developing novel therapeutic targets." (PMID 40092486, 2025). "To further determine the clinical significance of S100A2, we collected tumor samples from 110 ccRCC patients." (PMID 40011447, 2025). "Conversely, in other malignancies such as non-small cell lung cancer, colorectal cancer, endometrial cancer, and pancreatic cancer, S100A2 appears to play a role in promoting tumor initiation and progression." (PMID 40011447, 2025). "In EC, multiple S100 proteins, including S100A1, S100A2, S100A4, S100A8, and S100A9, have been implicated in tumor proliferation, invasion, epithelial–mesenchymal transition (EMT), and response to chemotherapy." (PMID 41303754, 2025). "Inhibiting the STING pathway reverses the effects of S100A2 knockdown, highlighting the pathway’s role in tumor progression." (PMID 39949780, 2025). "S100A2 demonstrates tumor-inhibiting properties, as observed in studies on liver cancer and squamous cell carcinoma." (PMID 40011447, 2025). "In this study, we first elucidate the tumor-promoting function of S100A2 in ccRCC by reprogramming glycolysis." (PMID 40011447, 2025). "Among these genes, several immune system genes, such as COL18A1, S100A2, ITGA4, HLA‐C, and ADCYAP1, have previously been linked to tumor progression in PCa." (PMID 39162297, 2024). "The existing body of research that highlights S100A2's predominant nuclear localization lends credence to its proposed function as a tumor suppressor." (PMID 38684596, 2024). "Prognosis analysis further supported the involvement of ECM1, MMP3, and S100A2 in the development of BC, as indicated by their elevated levels in human tumor biopsies." (PMID 38402239, 2024). "Identified in a screening for tumor suppressor genes and present in low levels in normal cells, S100-A2 is stimulated in keratinocytes by epidermal growth factor." (PMID 38473953, 2024). "In parallel, we found a positive relationship with CD163 M2-like macrophages suggesting the contribution of immune activation when tumours have higher S100A2 expression." (PMID 37476187, 2023). "The results demonstrated that tumours with high cytoplasmic S100A2 were enriched for infiltration of CD3+FOXP3+ cells (positive, P < 0.001) and CD163+ cells (positive, P = 0.009)." (PMID 37476187, 2023). "RNA transcriptomic analysis showed a gene significantly associated with the low cytoplasmic S100A2 group (AKT3, TAGLN, MYLK, FGD6 and ETFDH), which correlated with tumour development and progression." (PMID 37476187, 2023). "Multiplex immunofluorescence (mIF) was performed to further study and confirm the immune infiltration in tumours with low and high cytoplasmic S100A2." (PMID 37476187, 2023).
tumor (continued). "S100A2 was discovered as the EF-hand calcium-binding protein by subtractive hybridization to screen tumor suppressor genes in cancerous versus healthy breast epithelial cells." (PMID 37758734, 2023). "We found elevated levels of S100A2 in tumors, correlated with tumor grades, but the promoter methylation level of S100A2 decreased in primary tumors, and the difference in disease was nonsignificant." (PMID 37758734, 2023). "GSEA analysis identifies the enriched anti-tumour and immune activity group of genes in high cytoplasmic S100A2." (PMID 37476187, 2023). "The group with S100A2 overexpression exhibited markedly elevated tumor numbers compared with the control group, whereas the tumor numbers of the S100A2 knockdown group reduced." (PMID 37758734, 2023). "The immunes signature gene set database was utilised to identify the different immunogenic patterns between tumours with low and high cytoplasmic S100A2." (PMID 37476187, 2023). "RNA expression was determined using TempO-Seq technology and tumours classified as either low (n = 175) or high (n = 435) for the S100A2 protein expression were compared using R packages for clustering analysis." (PMID 37476187, 2023). "Hierarchical clustering analysis was used to generate a heatmap for the top 50 differentially expressed genes comparing tumour cases with low S100A2 to those with high S100A2 protein expression." (PMID 37476187, 2023). "For instance, S100A2 functions either as a tumor promoter or tumor suppressor, depending on the type of cancer." (PMID 37627239, 2023). "In this section, we describe the different roles of S100A2 in different organ-derived malignant tumors to better understand the role of S100A2 in tumor development." (PMID 35885660, 2022). "Although S100A2 has a tumor suppressor function, the recently updated research focusing on the prognostic impact of S100A2 revealed the various influences of S100A2 in human malignancies, in addition to the inflammatory diseases." (PMID 35885660, 2022). "S100A2 overexpression enhances glucose metabolism and cell proliferation owing to the advantage of tumor development in vivo." (PMID 35885660, 2022). "Consistently, the overexpression of S100A2 in NSCLC tumor cells enhances transendothelial migration and distant organ metastasis in vivo." (PMID 35885660, 2022). "Although S100A2 is a tumor suppressor, we describe the various influences of S100A2 on cancer and inflammatory diseases." (PMID 35885660, 2022). "Our review shows that S100A2 functions as a tumor suppressor; however, the influence of its expression is completely different in different types of malignant tumors." (PMID 35885660, 2022). "Although S100A2 has a tumor suppressor function, the recently updated research focusing on the prognostic impact of S100A2 revealed the various influences of S100A2 in human malignancies in addition to inflammatory diseases." (PMID 35885660, 2022). "Here, we constructed a new prognostic nomogram using age, clinical stage, histologic grade, tumor invasion, histological type and S100A2 levels as indicators that can be used by physicians to improve the accuracy of identifying high-risk patients." (PMID 35042454, 2022). "Silencing S100A2 expression in head and neck squamous cell carcinoma reveals cisplatin sensitivity in acquired and naturally cisplatin-resistant tumor cells in vivo." (PMID 35885660, 2022). "Consistently, another study showed that the expression of S100A2 protein is correlated with tumor differentiation and lymph node metastasis in vivo." (PMID 35885660, 2022). "Comprehensive analysis of S100A2 immunohistochemical scores and clinicopathologic information revealed that tumor with high S100A2 expression experienced higher T stage and poorer differentiation." (PMID 34887861, 2021). "Meanwhile, NK cells, another major tumor killer cells, showed a similar trend in S100A2 high expression group." (PMID 34887861, 2021).
tumor (continued). "Numerous S100 proteins are known for being overexpressed in cancers, among which S100A2 is believed to mainly act as a tumor-suppressive agent." (PMID 34746237, 2021). "EGF-stimulated EGFR phosphorylation induces the S100A2 expression, and S100A2 exhibits antitumor activity by reducing the rate of tumor growth when overexpressed in nude mice with NCI-H2172 cell tumor xenograft model." (PMID 34239729, 2021). "Among them, CT8+T cells, the immune cell with the most prominent tumor killing ability, were significantly reduced in S100A2 high expression group, which partially explained the poor prognosis of patients with high S100A2 expression." (PMID 34887861, 2021). "According to comprehensive analysis of immunohistochemical scores, it was confirmed that patients with high S100A2 expression had higher PD-L1 expression in tumor tissues." (PMID 34887861, 2021). "Meanwhile, we calculated the tumor mutation burden (TMB) of each sample and found that the TMB was higher in the group with high S100A2 expression (P <0.05)." (PMID 34887861, 2021). "A controversial role in carcinogenesis has been described for S100A2, which has been proposed both as a tumor suppressor and a tumor promotor." (PMID 32344524, 2020). "For instance, in oral carcinoma, S100A2 acts as a tumor-suppressor, while tumor-promoter in lung carcinoma." (PMID 30558666, 2018). "S100A2 has been identified as a markedly downregulated gene in tumor-derived mammary epithelial cell lines and was assumed as a tumor suppressor gene." (PMID 30558666, 2018). "Among the ubiquitous S100 protein members, the S100A2 is the one showing a higher index of fold increase (about 30 times) on the average of non-tumor tissues." (PMID 28686225, 2017). "While S100A2 is expressed in many normal tissues, its aberrant expression in a number of tumor tissues has been reported." (PMID 26097874, 2015). "S100A2, a member of the S100 protein family, is known to be downregulated in a number of human cancers, leading to its designation as a potential tumor suppressor gene." (PMID 26097874, 2015). "The S100 proteins are almost exclusively present in the tumor extracts, even though some S100 members are expressed at low, or very low levels, for example S100A2, S100A4 and S100A8." (PMID 20815901, 2010). "Other S100 proteins are downregulated in tumours and have putative tumour suppressor roles, including S100A2 and S100A6 in prostate cancer." (PMID 17579622, 2007). "S100A2 methylation was detected in all normal cerebella, cell line and tumour samples tested; however, significant variability in methylation patterns and levels were observed in all sample groups." (PMID 17579622, 2007). "S100A2 is a calcium-binding protein that is down-regulated in many tumor types and is thought to possess tumor suppressor activity." (PMID 17500590, 2007). "Surprisingly, based on a number of studies of gene expression, S100A2 is generally considered to be a tumour suppressor gene." (PMID 15467767, 2004). "A total of 29 out of these 47 tumours (62%) strongly expressed S100A2 either in the nucleus (26 out of 47) or the cytoplasm (28 out of 47)." (PMID 15467767, 2004). "Although ΔNp63 expression correlated well with S100A2 expression – in that tumours strongly expressing TP73L tended to strongly express S100A2 – there was not an exact correlation." (PMID 15467767, 2004). "Increased expression of the transcript appeared to be accompanied by increased protein expression and using IHC, 62% of tumours showed strong expression of S100A2 protein." (PMID 15467767, 2004). "In this second series, S100A2 was strongly expressed in 76% (35 out of 46) of tumours, more frequently in squamous cell than adenocarcinomas (P<0.002)." (PMID 15467767, 2004). "Such a model would suggest that tumour S100A2 expression is related to the expression pattern of the cell-type of origin and not simply a characteristic of squamous cell differentiation." (PMID 15467767, 2004).
tumor (continued). "A number of genes have recently been shown to be expressed strongly in tumours, preneoplastic bronchial lesions and in the normal multipotent basal epithelial cells of the airway: examples include S100A2, TP73L and SERPINB5." (PMID 15467767, 2004). "Having previously demonstrated that the S100A2 transcript and protein are strongly expressed in tumour cells compared to normal lung, we sought to examine protein levels in the independent patient series." (PMID 15467767, 2004). "S100A2 transcripts were consistently detected in normal tissues, but were present at much lower levels compared to tumour samples." (PMID 15467767, 2004). "It has been suggested that S100A2 is a tumour suppressor gene and that its expression is downregulated in neoplastic cells." (PMID 15467767, 2004). "Using this approach, we have demonstrated that S100A2 gene products are over-represented in the tumours of most NSCLC patients compared to matched normal lung tissue." (PMID 15467767, 2004). "Levels of S100A2 transcript in tumour samples of this new series were compared to those in matched normal lung, by cmRT–PCR." (PMID 15467767, 2004). "One of the sequences so highlighted, S100A2, a gene considered to be a tumour suppressor, was found to be over-represented in tumour samples compared to matched normal lung." (PMID 15467767, 2004). "Using semiquantitative RT–PCR and essentially confirming our earlier observations, 76% of NSCLC patients examined showed a two-fold or greater over-representation of S100A2 transcripts in their tumour sample compared to matched normal lung." (PMID 15467767, 2004). "S100A2 is a potential tumor suppressor in multiple cancer types, but its role remains under debate." (PMID 41513619, 2026). "Multiple S100 proteins, including S100A2, S100A4, S100A8, and S100A9, are significantly upregulated in EC compared with those in the normal endometrium, and their expression has been linked to tumor proliferation, invasion, and progression." (PMID 41303754, 2025). "Regarding tumor metastasis, S100A2 plays a significant pro-metastatic role in ccRCC." (PMID 40011447, 2025). "Furthermore, an 11-gene signature derived from the S100A2-positive tumor subset consistently correlated with unfavorable overall survival." (PMID 40092486, 2025). "Given that MMP1 and S100A2 have been identified as important factors in the onset and development of PDAC, further research should investigate the role of MMP1/S100A2 in fostering a tumor-supportive microenvironment, particularly concerning CCL2+ macrophages and OMD+ fibroblasts." (PMID 40092486, 2025). "Overall, key cell subsets including OMD+ fibroblasts, CCL2+ macrophages, and S100A2+ tumor cells might collectively contribute to a pro-tumor microenvironment conducive to LNM in PDAC." (PMID 40092486, 2025). "Based on the hypothesis that S100A2 influences glucose metabolism to promote tumor metastasis, we performed 1H-NMR-based metabolomics on OSRC-2 cells." (PMID 40011447, 2025). "Furthermore, S100A2+ tumor subset supported the homeostasis of FOXP3+ regulatory T cells with CD86-CD28/CTLA-4 (cytotoxic T lymphocyte-associated protein 4) interaction." (PMID 40092486, 2025). "Secondly, we found a S100A2+ tumor subset which fueled lymph node metastasis in PDAC." (PMID 40092486, 2025). "Notably, the S100A2+ tumor cell subset also drives the progression from tumor precursors to PDAC by activating Notch2 signaling." (PMID 40092486, 2025). "To validate the link with the proliferation signatures obtained by RNAseq, we performed staining for Ki‐67 in these 10 tumors and calculated the proliferation index in tumor cells (Qupath‐based computer‐assisted Ki‐67 count) and found that proliferation was higher in S100A2 tumors (p = 0.04)." (PMID 39935174, 2025). "Furthermore, S100A2 staining scores were higher in tumor cells from LNM sites compared with corresponding primary tumors." (PMID 40092486, 2025).
tumor (continued). "Notably, CKS1B+ neoplasm significantly enriches pathways related to cell proliferation, while S100A2+ neoplasm is markedly enriched in angiogenesis and epithelial–mesenchymal transition pathways." (PMID 38946232, 2024). "In brief, FOS+ S100A2+ Teff subpopulation may play crucial roles in regulating cellular migration, inflammatory responses, and immune reactions within the tumor microenvironment." (PMID 39234254, 2024). "This analysis revealed that seven cell populations exhibited a significant correlation with poorer patient outcomes, including tumor cell cluster 3 (highly expressing S100A2), cluster 8 (TK1), cluster 10 (PTTG1), cluster 12 (IGFBP5), cluster 13 (ISG15), cluster 16 (UPP1), cluster 17 (IL13RA2)." (PMID 38331898, 2024). "The transcriptomic data showed that genes differentially expressed in tumour with low cytoplasmic S100A2 groups may correlate with disease development and progression." (PMID 37476187, 2023). "In the tumor array, S100A2 transcription levels were consistently very low." (PMID 37627239, 2023). "Furthermore, it has been discovered that S100A2 contributes to tumor growth by regulating the tumor microenvironment and evading the immune system." (PMID 38260844, 2023). "S100A2 is widely recognized as a putative tumor suppressor gene that inhibits cell proliferation." (PMID 37758734, 2023). "Since S100A2 plays a role in regulating tumor development in almost all tumors, the interaction of S100A2 with erythropoietin might be important in certain conditions, such as erythropoietin-dominant tumor development." (PMID 35885660, 2022). "The potential importance of the S100 family of calcium binding proteins was further seen within a subpopulation of tumor-enriched epithelial cells defined by high expression of S100A2, which increased post-chemotherapy and whose expression correlated with poor response." (PMID 36253784, 2022). "However, some members of the S100 family have been reported to be tumor suppressors, including S100A2, S100A11, and S100A9." (PMID 35760899, 2022). "Further, BRCA1 can interact with ΔNp63 proteins, enhancing S100A2 expression and tumor growth." (PMID 35885660, 2022). "In contrast, erythropoietin can interact with S100A2 to enhance tumor development." (PMID 35885660, 2022). "Several genes within the S100 family were increased in tumor cells including a tumor-enriched cluster expressing S100A2 together with KRT15 and COL17A1 which are notable as markers of a quiescent stem/progenitor cell population in the most basal layer of the human esophagus." (PMID 36253784, 2022). "S100A2 is thought to act both as a tumor suppressor and as an oncogene depending on the tumor type, suggesting that S100A2 may exert its effects through different mechanisms." (PMID 35042454, 2022). "Compared with tumor-adjacent tissues, the S100A2 expression was indeed higher in PCa samples." (PMID 34568039, 2021). "In addition, it was worth noting that the expression of S100A2 was positively correlated with the activation of dendritic cells, which played a pivotal role in anti-tumor immunity." (PMID 34887861, 2021). "There is controversy about the actions of S100A2 in tumor development." (PMID 34527585, 2021). "In addition, it was discovered the expression of S100A2 in tumor tissues was remarkably positively correlated with the expression of PD-L1 (P = 0.001, r = 0.25) and CTLA-4 (P <0.01, r = 0.23), especially PD-L1." (PMID 34887861, 2021). "In our study, we found that the expression of PD-L1 was significantly increased in patients with high S100A2 expression, suggesting that patients with high S100A2 expression may have fewer T cells infiltration in tumor microenvironment." (PMID 34887861, 2021). "Notably, the expression of S100A2 was significantly increased along with the progression of tumor grade, AJCC_stage, age and T stage." (PMID 34887861, 2021).